FOXP3 (forkhead box P3)
Diseases named in the same sentence as FOXP3 in open-access papers (continued):
Sharing a sentence is not in itself a finding about the gene and the disease.
melanoma (continued). "We performed in vitro experiments with human healthy donor PBMC and clinical samples from patients with lung cancer, mesothelioma and melanoma, and tested our approach in vivo using ASO FOXP3 in syngeneic murine cancer models and in humanized mice." (PMID 39234236, 2024). "Foxp3-DTR-KI mice treated with diphtheria toxin also suppressed B16F10 melanoma growth, indicating that selective Treg depletion mimicked total CD4 T cell depletion effects." (PMID 39470607, 2024). "Studies on melanoma have highlighted that IDO enzymes, by inducing FOXP3 release in the tumor microenvironment, promote effector T-cell suppression and generation of regulatory T cells (Tregs)." (PMID 38791968, 2024). "Paired samples from patients with melanoma collected either before treatment or after disease progression revealed that the densities of VISTA- and FOXP3-expressing cells were both significantly increased in tumors after disease progression." (PMID 39482534, 2024). "In AYA melanomas, the expression of key gene markers for Tregs (CD3D, FOXP3) strongly correlated with CD3+FOXP3+ cell density (Spearman’s ρ = 0.74, P < 0.0001)." (PMID 38589406, 2024). "We also determined the intratumoral density of immune cell subsets in the melanoma metastases using 10 different markers (CD8, CD45RO, CD20, FOXP3, NKp46, CD103, CD134, CD137, PD-1, PD-L1)." (PMID 39766316, 2024). "TIL markers including FOXP3 and CD20 have also been added to the Immunoscore evaluation in melanoma." (PMID 39712007, 2024). "Intriguingly, we found an increase of FOXP3+ T cells in CTLA4res tumors as compared to PD1res and ICB naïve melanomas (P = 0.047)." (PMID 38594286, 2024). "On the other hand, TNF administration in the murine melanoma metastatic model increased metastasis and correlated with the infiltration of regulatory CD4(+)/Foxp3(+) T cells in the lungs." (PMID 39650654, 2024). "Recently, in cervical cancer and melanoma, elevated levels of CD8+FOXP3+ T cells were observed in responders to anti-PD-1 therapy." (PMID 36045586, 2023). "In patients with malignant melanoma, we found shorter PFS related to FoxP3 nuclear positivity (17.0 vs. 4.5 months, p = 0.048, HR 3.04, 95% CI 0.95–9.71) and CD68 positivity (15.0 vs. 4.1 months, p = 0.034, HR 3.21, 95% CI 1.02–10.1)." (PMID 36980787, 2023). "Using a melanoma model of adoptive T cell therapy (ACT), we show that FOXP3 overexpression in mature CD8 T cells improved their antitumor efficacy, favoring their tumor recruitment, proliferation, and cytotoxicity." (PMID 36045586, 2023). "When analyzing the malignant melanoma group, shorter median progression-free survival (PFS) was found in tumors positive for nuclear FoxP3 in tumor-infiltrating lymphocytes (TILs) (p = 0.048, HR 3.04) and for CD68 expression (p = 0.034, HR 3.2)." (PMID 36980787, 2023). "Relatively rare cells such as CD8 + FoxP3 + cells, which represent around 2.5% of all CD8 + cells in the melanoma TME, were also mapped." (PMID 35672823, 2022). "It has been shown in a cohort of primary melanoma samples from NYU and Vanderbilt that young patients acquire resistance to immunotherapy due to a reduction in FOXP3+ Treg cell population, while old patients (> 66 years) have a small CD8+ T cell population." (PMID 36135194, 2022). "Previously documented markers including FOXP3 (Tregs), CD163 (TAMs), CD33 (TANs), FAP (CAFs), MIA (melanoma), and ALDH1A1 (HNSC), were used for cell-type annotation." (PMID 35812726, 2022). "In contrast, in invasive primary melanoma biopsies, we observed many more CD4+ cells, among which we identified GATA3+FOXP3– cells, GATA3–FOXP3+ cells, and GATA3+FOXP3+ cells." (PMID 36107619, 2022).
melanoma (continued). "The elevated presence of peritumoral FoxP3+ lymphocytes predicts improved melanoma-specific survival (MSS), and peritumoral CD8+ and tumoral FoxP3+ lymphocytes correlate with improved OS and MSS." (PMID 36358637, 2022). "In an alternative comparison, among the FOXP3+CD4+ Tregs, the percentage of GATA3+ cells was elevated in invasive melanoma compared with in situ melanoma." (PMID 36107619, 2022). "To further explore the nature of GATA3+Foxp3–, GATA3+Foxp3+, and GATA3–Foxp3+ cells, we examined additional markers for Treg and Th2 cells in ILNs draining Braf/Pten/Tslp+/+ dorsal melanomas." (PMID 36107619, 2022). "Within the melanoma TME, we found a positive correlation between CD79A with FOXP3 and between TGF-β with FOXP3, gene expression." (PMID 35909944, 2022). "FoxP3 and IDO were immunohistochemically stained from 29 benign and 29 dysplastic nevi, 18 in situ -melanomas, 48 superficial and 62 deep melanomas and 67 lymph node metastases (LNMs) of CM." (PMID 34051744, 2021). "In this study, we analyzed the potential prognostic and/or predictive role of several TIL markers (CD3, CD8, FOXP3, GRZB and PD-L1) in primary melanoma and unmatched cutaneous metastases." (PMID 34066146, 2021). "Consistent with the increased proportions of metastatic melanoma patients expressing high levels of FOXP3, PRDM1 and CXCR5, we have detected TFR cells in melanoma across the different metastatic tissues." (PMID 34798898, 2021). "Thus, the association of IDO+ melanoma cells with high amounts of FoxP3+ Tregs and TAMs may not refer to the direct impact of IDO on Tregs and TAMs, but to a high overall immunological activity and strongly induced immune suppression in the tumor site." (PMID 34051744, 2021). "A meta-analysis of all-sites melanoma showed a favorable role of CD4+, CD8+, and FOXP3+ as prognostic factors." (PMID 33916279, 2021). "In syngeneic mouse tumor models, PDI-1 inhibited the growth of hPD-L1-expressing melanoma and NSCLC by increasing the abundance of effector CD8+ T cells and decreasing that of inhibitory FoxP3 CD4+ Tregs." (PMID 34054817, 2021). "In advanced melanoma, the potential prognostic value of CD3, CD8, CD20 and FOXP3 expression levels is being evaluated in patients treated with ipilimumab, and the correlation of marker expression profile with clinical outcome is ongoing." (PMID 35008245, 2021). "Melanoma specimens were stained for FoxP3 and IDO to examine the number and localization of FoxP3+ Tregs and IDO+ stromal immune cells." (PMID 34051744, 2021). "The number of FoxP3+ Tregs and IDO+ stromal immune cells were significantly higher in malignant melanomas compared with benign lesions." (PMID 34051744, 2021). "In univariate analysis of immunohistochemical features, FOXP3, CD4, CD8, PD-1, and Melanoma Institute of Australia (MIA) grading TILs (grade, density, and distribution) were correlated with survival." (PMID 33916279, 2021). "Previously, we conducted one of the first immunoscore studies in melanoma using a multiplex IHC approach, in order to evaluate the expression of CD3, CD8, CD20 and FOXP3 in metastatic lymph nodes." (PMID 34066146, 2021). "In a more recently published systematic review, a favorable prognostic role of the CD3+, CD4+, CD8+, FOXP3+, and CD20+ TILs on the overall survival of melanoma patients was confirmed." (PMID 33854972, 2021). "We used triple-color immunohistochemistry to evaluate Foxp3 and GzmB expression in CD4+ TILs in patients with advanced melanoma prior to therapy and 3 weeks post-treatment with ipilimumab and melphalan." (PMID 31924474, 2020). "Mice with Foxp3-conditional KO of HIF-2α are resistant to growth of MC38 colon adenocarcinoma and metastases of B16F10 melanoma." (PMID 33024109, 2020). "All phenotypic and functional markers of T cells—CD3E, CD4, CD8B, FOXP3, GZMB, PRF1 and TBX21—were expressed at higher levels in melanoma patients with high ETV7 expression." (PMID 33424867, 2020).
melanoma (continued). "In melanoma and in non-small-cell lung cancer (NSCLC), CD8+FoxP3+ T cells were described as a population of early effector T cells." (PMID 30755279, 2019). "To determine how these CD4+Foxp3+IL-10+ cells affect the anti-metastatic effects of metformin, we injected C57BL/6J mice with anti-CD25 1 day prior, and 1 and 7 days after B16F10 melanoma inoculation." (PMID 29899823, 2018). "Composite images were analyzed using inForm® software to define cells as either melanoma (SOX10+) or T cells subsets (CD3+CD4+, CD3+CD8+, CD3+CD4+FoxP3+, CD3+ CD4−CD8−)." (PMID 30042403, 2018). "In humans, we found circulatory IL-10 strongly elevated in late stages of melanoma positively correlating with the circulatory elevated T lymphocyte CD4+ and CD25+ with FOXP3 expression." (PMID 29318162, 2017). "Our results revealed that several molecules such as Foxp3 and CD39/CD73 are shared by both, Treg and melanoma cells and that those Treg specific marker molecules are highly expressed on different melanoma cell lines compared to normal melanocytes." (PMID 27248166, 2016). "In metastatic prostate cancer and advanced melanoma patients, ipilimumab treatment induced a significant increase in Ag-specific humoral and CTL responses, while levels of suppressive FoxP3+ Tregs remained stable or were expanded." (PMID 27509527, 2016). "Decreased immune response in the positive sentinel LN from melanoma patients is featured by decreased CD8+ effector T cells and stimulatory CD11c+CD86+ DCs, and increased forkhead box P3+ (Foxp3+) regulatory T cells." (PMID 28036019, 2016). "To test this possibility, we identified four representative T/NK modules that tracked with survival differences in distinct tumor types (FOXP3.mod, PDCD1.mod, FLT3LG.mod and KLRB1.mod for bladder, head and neck, kidney and melanoma, respectively)." (PMID 26398410, 2015). "Melanoma, head and neck, and bladder tumors expressing high levels of FLT3LG.mod, PDCD1.mod and FOXP3.mod transcripts, respectively, also expressed significantly higher levels of LCK protein." (PMID 26398410, 2015). "Multispectral fluorescent immunohistochemistry with a panel including CD3, CD8, FoxP3, CD163, PD-L1 was used to analyze the tumor microenvironment in 17 patients with melanoma among our 36-patient cohort to predict successful TIL generation." (PMID 26500776, 2015). "In addition, whether FOXP3 promotes or inhibits the growth of melanoma cells is unknown." (PMID 24406338, 2014). "Our group already quantified Foxp3 expression using qPCR and Foxp3 appeared as an independent prognostic factor for PFS in stage III melanoma patients with invaded lymph nodes." (PMID 24741578, 2014). "FOXP3 expression was detected by immunohistochemistry (IHC) in 12% (18/146) of stage III and IV melanomas." (PMID 24406338, 2014). "In a human melanoma study, for example, CD4+Foxp3+ Treg cells infiltrating tumor tissue not only displayed upregulated expression of ICOS but also exhibited a more potent suppressive activity compared to those derived from circulating blood cells." (PMID 23874336, 2013). "In many human cancers such as cervical, ovarian, melanoma, lymphoma, gastrointestinal, and head and neck cancer, level of tumor infiltrating CD8 versus CD4+Foxp3+ Treg cells provides strong prognostic factor." (PMID 23533812, 2013). "In the present study we examined the prevalence of several immune cell types: OX40+ activated T lymphocytes, FOXP3+ regulatory T cells, DC-LAMP+ mature DCs and CD123+ plasmacytoid DCs in sentinel lymph nodes of melanoma patients." (PMID 23418928, 2013). "In the context brain metastasis arising from melanoma cells, the novel STAT3 inhibitor, WP1066, reverses immune suppression through the inhibition of FoxP3 induction in peripheral T cells and down-regulation of Foxp3 expression in nTreg." (PMID 23720663, 2013).
melanoma (continued). "We confirmed that Foxp3-positive CD4 T cells are enriched among tumor-infiltrating lymphocytes (TIL) and splenocytes (SPL) in B16 murine melanoma-bearing C57BL/6 Foxp3EGFP mice." (PMID 22112546, 2011). "The authors showed that ABCB5+MHC class II+ cells displayed higher capacity than ABCB5- MHC class II-negative melanoma cells to inhibit IL-2-dependent T-cell activation and support the induction of CD4+CD25+FoxP3+ regulatory T cells." (PMID 21526207, 2011). "The general trend observed in consecutive stages of melanoma was a gradual build up of the immunosuppressive markers ILT3, FOXp3, IL-10 and IDO, with peak expression occurring in positive SLN." (PMID 17565341, 2007). "Both FoxP3 and ILT3 showed similar expression patterns and were detected in all four melanoma sites, but were highest in positive SLN." (PMID 17565341, 2007). "As with ILT3 and FOXp3, expression of both IL-10 and IDO increased with melanoma progression from skin into the lymph nodes, the peak occurring in positive SLN." (PMID 17565341, 2007). "As well as FOXp3 we have also demonstrated expression of ILT3, a marker of tolerogenic DCs and have correlated markers of local immunosuppression with melanoma progression." (PMID 17565341, 2007). "To test whether Foxp3 degradation would compromise the tumoral Treg function, we implanted B16-OVA melanoma cells in the flank of Foxp3AIDR26TIR1(F74G) and Foxp3AIDR26WT mice." (PMID 41062655, 2025). "We noted a significant CD8+ T cell–dependent increase of CD4+Foxp3+ Tregs in the tumor bed of LLC- but not B16 melanoma–bearing mice." (PMID 40553564, 2025). "In conclusion, we report that patients with melanoma lymph node metastases with low FOXP3 TIL count and negative tumour cell PD-L1 expression have reduced survival, and that these metastases also have a low CD8 TIL count." (PMID 39883679, 2025). "In summary, we demonstrated that high FoxP3 expression in TILs has a negative predictive value for therapy with PD-1 inhibitors in malignant melanoma and NSCLC." (PMID 36980787, 2023). "Consistent with this, our study confirmed that miR-155 downregulates CTLA4 at the mRNA level without interfering with FOXP3 expression in circulating Treg cells from melanoma patients." (PMID 37197667, 2023). "Furthermore, LAG-3 is expressed on CD4 (+) CD25 (high) Foxp3 (+) T cells, which represent an expanded cell subset that secretes immunosuppressive cytokines such as IL-10 and TGF-β1 in patients with melanoma and colorectal cancer." (PMID 36829496, 2023). "In our previous study, we found that treatment with low-dose curcumin (5 mg/kg) did not reduce the tumor size and Foxp3+ Tregs population in the tumor microenvironment in B16-F10 melanoma-bearing mice." (PMID 36814928, 2023). "Use of this platform facilitated the robust assessment of the intensity of in situ PD-1 and PD-L1 expression on different cell types within the melanoma TME, with 41 combinations of expression patterns identified using six markers (PD-1, PD-L1, CD8, FoxP3, CD163, and Sox10/S100)." (PMID 35672823, 2022). "TGF-β-expressing B cells in the melanoma tumor microenvironment assembled in clusters and interacted with T cells via lymphoid recruitment (SELL, CXCL13, CCL4, CD74) signals and with Tregs via CD47:SIRP-γ, and FOXP3-promoting Galectin-9:CD44." (PMID 35909944, 2022). "PD-1 blockade reversed the increased expression of PD-1 and PD-L1 on human melanoma antigen-specific CTL by Tregs, rescued INF-γ expression by melanoma antigen-specific CTL that were diminished by Tregs, and resulted in the downregulation of intracellular FoxP3 expression by Tregs." (PMID 34832887, 2021). "FoxP3+ Tregs also seems to contribute to the immunosuppressive TME in CM, but their significance in melanoma progression remains unclear." (PMID 34051744, 2021).
melanoma (continued). "In single-cell RNA-seq dataset which was originated from melanoma tissue (GSE72056), we downloaded the TPM dataset file and sorted any values more than 3 TPM for cells that highly expressed Foxp3 transcripts and excluded invalid TPM values for Pdcd1 and Prkaa1 expression." (PMID 34649584, 2021). "Moreover, the number of both FoxP3+ regulatory T cells and IDO+ stromal immune cells was shown to be more abundant in malignant melanomas, compared to benign lesions." (PMID 34051744, 2021). "The abundance of CD8+ T cells and FoxP3+ T regulatory cells (Tregs), as well as PD-L1 expression by tumor and stromal cells in the tumor microenvironment (TME), are predictors of prognosis and response to immunotherapy in human NSCLC and melanoma." (PMID 34054817, 2021). "Moreover, in the B16 melanoma mouse model, the DC vaccine exhibits a significant antitumor effect by enhancing the CTL response and decreasing the percentages of FOXP3+ Tregs." (PMID 34806028, 2021). "Significantly increased frequencies of CD25+ cells that include both FoxP3+ and FoxP3- populations, were observed for CD4+ (p = 0.01) and CD4-CD8- (p = 0.0038) T cell subsets in blood from canine melanoma patients (n = 16) compared to healthy controls (n = 20)." (PMID 34926643, 2021). "The inhibitory function of VISTA in anticancer immunity was demonstrated in mice transplanted with melanoma, in which blocking of VISTA induced antitumor immunity by increasing tumor-specific CD4+ and CD8+ T cells and decreasing FoxP3+ regulatory T cells in the tumor microenvironment." (PMID 32873829, 2020). "To further interrogate the role of Tregs in melanoma brain tumor progression, we used transgenic C57BL/6 ‘DEREG’ mice in which the diphtheria toxin (DT) receptor is expressed downstream of the FoxP3 promoter, resulting in constitutive expression of this receptor on Tregs." (PMID 32690669, 2020). "Notably, cBioPortal analysis of TCGA data relevant to CCL22 expression in melanoma patients revealed a strong positive correlation between CCL22 and FOXP3 mRNA expression (Pearson = 0.66, Spearman = 0.77, P = 0.02)." (PMID 31911617, 2020). "In the present study characterization of some TIME features has demonstrated that both numbers of peritumoral and intratumoral FOXP3+ and CD8+ T cells as well as their ratio might be useful prognostic biomarkers in thin melanomas." (PMID 33117345, 2020). "Subsequent studies are needed to demonstrate if FOXP3 regulatory T cells inhibit regression in melanoma, as part of the immunogenic effect of melanoma cells, or if the lack of FOXP3-positive cells is the result of regression." (PMID 33274240, 2020). "Interestingly, metastatic lesions of melanoma patients who responded to ipilimumab were enriched for FcγRIII-expressing CD68+ “inflammatory” macrophages prior to treatment, while intra-tumoral FoxP3+ Tregs were depleted following treatment." (PMID 27509527, 2016). "FOXP3 expression has been observed in different cancer histotypes (NSCLC, breast, urinary bladder, tongue, gastric, esophageal, pancreas, colorectal, stomach, thyroid, glioma and melanoma)." (PMID 26604855, 2015). "To investigate the potential role of melanoma MMP-23 in contributing to conditions favorable to Tregs, we assessed the relationship between MMP-23 expression and Treg prevalence, as determined by the number of Foxp3+ cells." (PMID 25491880, 2014). "Recently, the subset of melanoma tumors characterized by the presence of T-cell infiltrates was found to demonstrate activation of three immunosuppressive markers: indoleamine-2,3-dioxygenase (IDO), PD-L1, and FoxP3+ regulatory T cells (Tregs)." (PMID 24743024, 2014). "The reasons for lack of response to IL-2 are starting to emerge: a recent study found that the T cell subset most induced by IL-2 in melanoma patients is regulatory T cells (Treg) expressing positive for CD4, CD25, Foxp3 and the inducible T cell costimulator (ICOS)." (PMID 24743024, 2014).